Y_RNA (Y RNA )
Gene: Miscellaneous RNA gene on chromosome 20 (25,214,698 to 25,214,798, forward strand). Ensembl gene ENSG00000202414.
Homologues: Orthologues: chimpanzee Y_RNA (99% identical), macaque Y_RNA (93% identical). Paralogues in human: Y_RNA (90% identical), RNY3 (88% identical), RNY3P1 (88% identical), Y_RNA (88% identical), Y_RNA (87% identical), Y_RNA (86% identical), RNY3P11 (85% identical), Y_RNA (85% identical), Y_RNA (84% identical), RNY3P14 (83% identical), Y_RNA (83% identical), Y_RNA (82% identical), and 96 more.